NOD2 (nucleotide binding oligomerization domain containing 2)
Diseases named in the same sentence as NOD2 in open-access papers (continued):
Sharing a sentence is not in itself a finding about the gene and the disease.
neurological diseases (1 paper, 2024). "Several neurological diseases are known to be associated with microglia-driven inflammation, in which NOD2 and/or TLR4/myeloid differentiation primary response protein 88 (MyD88) signaling pathways are actively involved." (PMID 39519307, 2024). "Our data could have important implications for understanding the complex interplay between NOD2- and TLR4-mediated inflammatory pathways in microglia, which is relevant for many neurological diseases associated with dysregulated microglial neuroinflammatory responses." (PMID 39519307, 2024).
respiratory diseases (1 paper, 2024). "Next, complementary analyses identified nine DMGs (LTA, STAT3, IKBKG, IRAK1, NOD2, TLR2, TNFRSF1A, and IKBKB) that might be involved in the immune response of XJB cattle infected with respiratory diseases." (PMID 38732144, 2024).
vasculopathy (1 paper, 2021). "Other examples of autoinflammatory disorders with disease-causing mosaicism in genes known to cause germline disease include Blau syndrome (NOD2), tumor necrosis factor receptor associated periodic syndrome (TRAPS, TNFRSF1A), and STING-associated vasculopathy with onset in infancy (SAVI, TMEM173)." (PMID 33864184, 2021).
NOD2 also shares sentences with these, for which no sentence is quoted: granulomatous dermatitis (4 papers); non-Hodgkin lymphoma (4); polyarthritis (4); systemic lupus erythematosus (4); vitamin D deficiency (4); cerebral artery (3); liver disease (3); lymphoma (3); psoriatic arthritis (3); pulmonary sarcoidosis (3); staphylococcus aureus infection (3); acne (2); allergies (2); angiitis (2); arthropathy (2); autoimmune myocarditis (2); autosomal dominant disease (2); cancers of the cervix (2); cervical carcinoma (2); chronic kidney disease (2); Cognitive impairment (2); colorectal tumors (2); congenital heart disease (2); diabetic cardiomyopathy (2); diarrhoea (2); G6PD deficiency (2); hyperlipidemia (2); hypertriglyceridemia (2); intestinal inflammation (2); pancreatic cancer (2).
A further 141 diseases each share a sentence with NOD2 in 2 papers or fewer.